IL6 (interleukin 6)
Diseases named in the same sentence as IL6 in open-access papers (continued):
Sharing a sentence is not in itself a finding about the gene and the disease.
Thrombocytosis (continued). "We used this model to analyze the effects of IL-6 that are exclusively transduced via the IL-6 trans-signaling pathway in combination with the oncolytic activity of the vaccinia virus, which included gain in body weight, levels of thrombocytosis and accelerated epidermal barrier repair." (PMID 22236378, 2012). "Several in vivo studies provide evidence that IL-6 induces thrombocytosis." (PMID 19936194, 2008). "However, even higher levels of IL-6 in the pleural fluid and of thrombocytosis were found in patients with tuberculous pleurisy." (PMID 9528833, 1998). "In thromboinflammatory disease, where IL-6 often co-rises with fibrin(ogen) degradation products and endothelial activation, targeting IL-6 may simultaneously mitigate coagulopathy, vascular inflammation, and secondary thrombocytosis." (PMID 41157266, 2025). "Also, various cytokines, such as IL-6, involved in granuloma formation promote platelet production, which could be the basis for thrombocytosis." (PMID 39062045, 2024). "Finally, tumours may also release thrombopoietin and interleukin-6—which stimulate thrombocytosis through various signalling pathways." (PMID 37046847, 2023). "The cause of tumor-associated thrombocytosis remains unclear, however, the tumor-associated production of granulocyte-macrophage colony-stimulating factor or thrombopoietin (TPO) mediated by interleukin-6 is considered to be responsible for the increase in PLT count observed in cancer patients." (PMID 25663931, 2015). "In other cancers IL-6 may also play a similar role in producing thrombocytosis." (PMID 23864954, 2013). "Due to the lack of IL-6-associated thrombocytosis and polyclonal hypergammaglobulinemia in iMCD-TAFRO phenotypes, their work has additionally suggested that elevated serum IL-6 may not be a sole pathological driver of hypercytokinemia in patients with iMCD-TAFRO." (PMID 38927535, 2024). "It has also been reported that the presence of IL-6 and high CRP in the liver triggers thrombocytosis and IL-6 induces differentiation from megakaryocytes to platelets and leads to an abnormal inflammatory response." (PMID 38218876, 2024). "IL-6 is likely to be the main driver, acting synergistically with other interleukins to increase thrombopoietin, of which visceral adipose tissue itself may be an additional source of thrombopoietin, which in turn stimulates megakaryocyte production, leading to thrombocytosis." (PMID 39544233, 2024). "Several evidence had revealed the main molecular mechanisms of thrombocytosis, including (i) tumor cells secret thrombopoietin (TPO), or interleukin-6 (IL-6) which can accelerate TPO production in the liver." (PMID 37170255, 2023). "Paracrine secretion of IL-6 from tumor cells stimulates the production of thrombopoietin (TPO), resulting in megakaryopoiesis and platelet genesis and leading to a status of thrombocytosis and hypercoagulability known as Trousseau’s syndrome." (PMID 37880772, 2023). "Laboratory testing revealed elevated interleukin (IL)-6 (40 pg/ml) and NT-pro-BNP (>3000 ng/l), hypocalcemia, increased serum inorganic phosphate and mild thrombocytosis." (PMID 36275728, 2022). "Severe RA correlates with thrombocytosis, hypergammaglobulinemia and elevated ESR and CRP levels in parallel with plasma and synovial levels of IL-6." (PMID 35886067, 2022). "In one study, orthotopic ovarian-mouse models revealed tumor-derived, interleukin-6-stimulated, hepatic-thrombopoietin (TPO) synthesis and paraneoplastic induction of thrombocytosis." (PMID 34367949, 2021). "Thus, elevated IL-6 may explain the thrombocytosis observed in IKK2-deleted mice." (PMID 33414459, 2021). "Our study confirmed thrombocytosis accompanying inflammation-related CRC and the crucial role of IL-6 in this process." (PMID 32867390, 2020). "The aim of our study was to evaluate the role of IL-6 in tumor development and thrombocytosis in mice with inflammation-induced CRC, using a CRISPR/cas9 IL-6 knockout (KO) strain." (PMID 32867390, 2020).
Thrombocytosis (continued). "All of their four patients had elevated levels of interleukin- (IL-) 1β, tumor necrosis factor-α, and IL-6, and they claimed that nonimmunoglobulinemic mediators could be a possible cause for the arterial thrombosis in addition to thrombocytosis and microangiopathic vasculopathy." (PMID 24716013, 2014). "Patients with thrombocytosis had a median VEGF serum concentration which was 3.2 times higher (P < 10−4) and a median IL-6 serum level which was 5.8 times higher (P = 0.03) than in other patients." (PMID 10360671, 1999). "TFNα, IL-1β, IL-6, and IL-8 are responsible for atherogenesis; especially TFNα is related to CVD and atherogenesis; IL-6 is related to thrombocytosis; IL-8 related with plaque formation; IL-1β related with vascular inflammation and correlate with atherogenesis." (PMID 39844544, 2025). "IL-6, as a key upstream regulator of JAK/STAT signaling, can activate STAT3 and related downstream molecules, enhance thrombopoietin expression, and drive excessive myeloid proliferation, ultimately leading to secondary (reactive) thrombocytosis." (PMID 41438978, 2025). "In dogs with carcinoma, the TPO and IL‐6 concentrations were not different between dogs with thrombocytosis and dogs with normal platelet count." (PMID 34881459, 2022). "However, IL-6 levels have been reported to correlate significantly with other markers of verified prognostic impact for MPM such as VEGF, thrombocytosis and CRP levels." (PMID 33562138, 2021). "HFD-treated 3 × Tg mice also exhibited increased platelet production (thrombocytosis) and MPV that could be partially attributed to elevated IL-6 and TPO, which induce MK differentiation into platelets." (PMID 34454596, 2021). "As high levels of serum IL-6 have been reported in USC, the same paraneoplastic pathway for thrombocytosis, and thus chemoresistance, may be in action." (PMID 32842701, 2020). "The plasma levels of TPO and of IL-6 correlated significantly with platelet count: patients with thrombocytosis had significantly higher IL-6 and TPO plasma levels, moreover, at given cutoff values, plasma IL-6 level and thrombocytosis have both been found to be independent prognostic factors." (PMID 32867390, 2020). "Many studies reported that some proinflammatory cytokines (one example to these cytokines is IL-6), which are elevated in FMF patients, might affect platelet volume by inducing thrombocytosis." (PMID 26464867, 2015). "The clinical manifestations of MCD are largely driven by activation of the interleukin-6 (IL6) signaling cascade, which results in an acute phase reaction with elevated erythrocyte sedimentation rate, C-reactive protein (CRP), fibrinogen, thrombocytosis and hypergammaglobulinemia." (PMID 23372742, 2013). "Typically there are also laboratory abnormalities: elevated serum concentration of gamma globulin and acute phase proteins, thrombocytosis, elevated ESR, low serum albumin level, proteinuria, and, sometimes, elevated IL-6, especially in the plasma cell systemic disease." (PMID 22014148, 2011). "The increase in TPO through IL-6, coupled with thrombocytosis has not yet been confirmed in CRC." (PMID 32867390, 2020). "The researchers found that TPO and IL-6 levels were high in patients who had thrombocytosis, as compared with those who did not, and that an increase in IL-6 levels positively correlated with plasma TPO levels and thrombocytosis, while negatively correlating with patient survival." (PMID 31991775, 2020). "Interestingly, it is known that IL-6 stimulates the synthesis of CRP and thrombocytosis." (PMID 25025065, 2014). "We hypothesized that IL‐6 and TPO concentrations would be higher in dogs with carcinoma compared to healthy dogs, and that IL‐6 and TPO concentrations would be higher in dogs with carcinoma and thrombocytosis when compared to dogs with carcinoma and normal platelet counts." (PMID 34881459, 2022). "Evaluate the concentrations of IL‐6 and TPO in dogs diagnosed with carcinoma with or without thrombocytosis." (PMID 34881459, 2022).
Thrombocytosis (continued). "Therefore, a prospective, real-life observational cohort study was conducted where paraneoplastic thrombocytosis was investigated within diabetic and nondiabetic CRC cohorts through the changes in platelet counts, plasma interleukin-6, and thrombopoietin levels." (PMID 35071777, 2022).
preeclampsia (160 papers, 2005 to 2026). Preeclampsia is a hypertensive disorder of pregnancy that is characterized by new-onset hypertension with proteinuria presenting after 20 weeks of gestation, and depending on mild or severe forms may initially present with severe headache, visual disturbances, and hyperreflexia. "Elevated IL-6 levels are also associated with complications such as preeclampsia, preterm birth, fetal growth restriction, and GD." (PMID 40062150, 2025). "Elevated levels of IL-6 in maternal serum are associated with a more severe and earlier onset of preeclampsia." (PMID 41375625, 2025). "In other words, the phagocytosis of necrotic trophoblast debris within the pulmonary capillaries triggers systemic activation of maternal endothelium, a hallmark of preeclampsia, via the secretion of soluble factors such as IL6." (PMID 39865240, 2025). "For instance, cord plasma IL-6 levels are reduced in fetal growth restriction associated with preeclampsia, and IL-6 is increased in the cord blood of neonates from obese mothers, but fetal growth/birthweight in these latter studies was not reported." (PMID 38671859, 2024). "The G allele of IL-6 was found to correspond with an increased risk for gestational diabetes and preeclampsia occurrence." (PMID 38893732, 2024). "As early as 2011, a meta-analysis sought to investigate the role of the inflammatory factors TNF-a, IL-6, and IL-10, assessing both their serum expression levels and the presence of polymorphisms in women with preeclampsia." (PMID 38893732, 2024). "Only four studies with total data from 396 women with preeclampsia and 507 controls were included in the final analysis for the -174 G/C polymorphism of IL-6." (PMID 38893732, 2024). "Several studies indicated a strong association between elevated placental leptin levels and preeclampsia (PE) pathogenesis and elevated serum interleukin-6 (IL-6) levels in PE patients." (PMID 38203306, 2023). "Elevated IL-6 concentration in pregnancy is related to the risk of miscarriage, preeclampsia, and preterm delivery." (PMID 37685739, 2023). "A large cohort study among preeclamptic women showed that vitamin D deficiency and IL-6 concentration had an independent positive correlation with the risk of preeclampsia." (PMID 37891486, 2023). "As a state of chronic inflammation, overweight will increase the risk of preeclampsia by means of activating macrophages, NK cells, and peripheral helper T cells within the placenta to produce inflammatory cytokines such as IL-6, IL-7, and TNF-α." (PMID 36833689, 2023). "More research is required to investigate the association between IL-6 gene polymorphism and preeclampsia risk at different gestational ages and also different populations." (PMID 35673309, 2022). "Significantly decreased placental mRNA expression of OAT4 was previously seen in pregnancies complicated with preeclampsia, a condition that is also associated with Th-17 activation and increased levels of IL-6, IL-17, and IL-23." (PMID 34203644, 2021). "They found that the EPA diet significantly lowered the plasma concentrations of the inflammatory factors interleukin-6 and tumor necrosis factor α, which can influence placental development and increase the risk of developing preeclampsia." (PMID 33603029, 2021). "Many proinflammatory markers have been implicated in preeclampsia including IL-6, IL-8, IL-10, IL-17, and TNF-α." (PMID 34780565, 2021). "Elevated levels of inflammatory cytokines are associated with preeclampsia, specifically; IL-6 and TNFa are increased in the maternal circulation and the placenta." (PMID 30464252, 2018). "Higher IL-6 was associated with preeclampsia in women with GDM (OR 1.85; 95% CI 1.17–2.92, per log2) but not in women without GDM (OR 1.25; 95% CI 0.87–1.79, per log2), although this was not significant in the interaction test (p = 0.18)." (PMID 30177064, 2018).
preeclampsia (continued). "There was, however, a trend for an association between the inflammatory mediator (IL-6) and preeclampsia in women who developed GDM." (PMID 30177064, 2018). "The increased maternal serum levels of IL-6 are associated with the severity and onset of preeclampsia." (PMID 24659862, 2014). "Recently, it was reported that recombinant interleukin-6 (IL-6) and TNFα were capable of activating endothelial cells, which is a hallmark of preeclampsia." (PMID 24060241, 2013). "Exposure to PM2.5 has also been linked to the release of cytokines, including interleukin-6, which are reported to be involved in pathogenesis of preeclampsia." (PMID 24021707, 2013). "Nonetheless, increasing tertiles of interleukin-6 and fibrinogen levels were associated with higher odds ratios for early-onset preeclampsia in women carrying one or more TLR4 or NOD2 mutations, compared to women with the wild-type TLR4 or NOD2 genotype." (PMID 18382655, 2008). "Nonetheless, the observed associations between high levels of interleukin-6 and fibrinogen and a positive history of early-onset preeclampsia were only moderately influenced by adjustment for interval between delivery and sampling." (PMID 18382655, 2008). "Combined positivity for any of the TLR4 and NOD2 allelic variants and high levels of interleukin-6 was 6.9-fold more common in women with a history of early-onset preeclampsia (95% CI 2.1–23.2) compared to controls." (PMID 18382655, 2008). "Additionally, vitamin C inhibits matrix metalloproteinase‐9 (MMP‐9) activity to maintain blood–brain barrier integrity and reduces pro‐inflammatory cytokine IL‐6 levels, alleviating neuroinflammation associated with gestational hypertension." (PMID 41476713, 2026). "Interleukin-6 involvement has been strongly suspected in various adverse conditions during pregnancy, and many studies have attempted to elucidate the relation of certain IL-6 gene polymorphisms in preeclampsia." (PMID 38893732, 2024). "There is emerging evidence that FGR and preeclampsia share common pathways, with a pro-inflammatory bias of increased levels of IL-6, IL-8 and TNF-α; however, FGR has been associated with decreased levels of the anti-inflammatory cytokine IL-10 in peripheral blood." (PMID 39124698, 2024). "The increased adrenergic tone from stress during pregnancy affecting circulating volume may cause ischemic strain and elevated levels of IL-6, which in turn may contribute to an increased risk of preeclampsia and autism." (PMID 39553377, 2024). "IL-6 increases during healthy pregnancy, and both decreased and elevated levels of this cytokine relative to normal are associated with pregnancy complications, including infertility, miscarriage, preterm birth, and preeclampsia." (PMID 37560162, 2023). "Therefore, there is a need to assess the association between iron status, hepcidin, IL-6 and preeclampsia in sub-Saharan Africa." (PMID 36909236, 2023). "In sub-Saharan Africa, there is a high prevalence of anaemia among pregnant women, which might have an effect on the association between iron status, hepcidin, IL-6 and preeclampsia." (PMID 36909236, 2023). "Furthermore, cytokines secreted by the M2b phenotype, including TNF‐α, IL‐1β, and IL‐6 have been associated with preeclampsia." (PMID 37269190, 2023). "For example, systemic elevation of IL-6 is associated with preeclampsia." (PMID 35348641, 2022). "Finally, the implication of IL-6 and IL-8 in pregnancy-associated pathological conditions, such as pregnancy loss, preeclampsia, gestational diabetes mellitus and infection/inflammation is discussed." (PMID 36498901, 2022). "Indeed, elevated levels of the adipokine IL-6 during pregnancy have been associated with various diseases in pregnancy, such as preeclampsia and gestational diabetes." (PMID 34948770, 2021). "Interestingly, PPARγ has a critical role in regulating inflammatory cytokines including TNF-α and IL-6, which were linked to preterm labor, miscarriage, and preeclampsia." (PMID 35011648, 2021).